ENSG00000142539 (novel protein)
Gene: Protein-coding gene on chromosome 19 (50,415,799 to 50,428,409, forward strand). Ensembl gene ENSG00000142539.
Genetic constraint (gnomAD): Loss-of-function variants: 18 observed, 32.55 expected, observed/expected ratio (o/e) 0.55, 90% interval 0.38 to 0.82. The synonymous counts are far from expectation, so gnomAD's model fits this gene poorly and the ratio says little. Missense variants: 500 observed, 432.82 expected, observed/expected ratio (o/e) 1.16, 90% interval 1.07 to 1.24. Synonymous variants: 252 observed, 197.13 expected, observed/expected ratio (o/e) 1.28, 90% interval 1.15 to 1.42.